IL10 (interleukin 10)
Diseases named in the same sentence as IL10 in open-access papers (continued):
Sharing a sentence is not in itself a finding about the gene and the disease.
leukemia (continued). "Interestingly, the Tregs A subpopulation is positive for already reported markers of CLL-related Tregs, including IL-10, LAG-3, granzyme B, EOMES, as well as share a unique gene expression signature of chemokines that may support leukemia progression and formation of leukemic microenvironment." (PMID 35296093, 2022). "Intriguingly, cytokine profiling from on-chip tests demonstrated that 4-1BBζ-CAR secreted more IL-13 (a Th2 cytokine), and CD28ζ-CAR and ICOSζ-CAR secreted more IL-10, whereas this is not the case for 2D tests with respective co-cultures of CAR T cell and leukemia blast." (PMID 37131801, 2023). "Intriguingly, cytokine profiling from on-chip tests demonstrated that 4-1BBζ-CAR secreted more interleukin (IL)-13 (a TH2 cytokine), and CD28ζ-CAR and ICOSζ-CAR secreted more IL-10, which may not be clearly observed in simple 2D tests with respective co-cultures of CAR T cells and leukaemia blasts." (PMID 40595437, 2025).
injury (72 papers, 2012 to 2025). Damage inflicted on the body as the direct or indirect result of an external force, with or without disruption of structural continuity. "IL-10 is significantly decreased in patients predisposed to developing severe knee OA after knee trauma." (PMID 34360771, 2021). "Liver injury was significantly associated with higher levels of interleukin (IL)-6 and IL-10 (p < 0.05)." (PMID 34307393, 2021). "Activated M1 phenotype microglia produce proinflammatory cytokines such as TNF-α, IL-1β, and IL-6; M2 phenotype microglia produce brain-derived neurotrophic factor and IL-10, which has been associated with neuroprotection after brain injury." (PMID 28529954, 2017). "The specific loss of IL10 in B cells can lead to increased expression of proinflammatory cytokines, persistent leukocyte infiltration and prolonged alveolar barrier damage in a mouse model of acute lung injury." (PMID 39896814, 2024). "Indeed, cytokines such as TNF-α-, NO, interleukin 1beta, IL-6, and IL-10 levels are increased in response to acute liver injury caused by free radical production." (PMID 35684137, 2022). "In addition to decreasing IL-6 and IL-8 levels and the infiltration of polymorphonuclear cells, NaHS increases plasma levels of IL-10 in an animal model of induced acute lung injury, and administering IL-10 to IL-10 deficient mice in turn restores H2S production and homocysteine metabolism." (PMID 34572292, 2021). "Therefore, we aimed to investigate whether other anti-inflammatory mechanisms may be involved as upregulation of IL-4 and IL-10, as was recently suggested in association with treatment of acute lung injury or osteoarthritis." (PMID 26640325, 2015). "Studies have demonstrated that Treg and γδT cells are activated and migrate to the damaged area following a ischemic brain injury, where they rapidly secrete IL-10 and IL-17, respectively." (PMID 40291783, 2025). "They observed no changes in TNF, IFN-γ, MIP-1α, and MIP-1β levels in healthy volunteers or trauma patients but did note an increase in IL-8 levels as well as small decreases in IL-6, IL-10, MCP-1, and IP-10 in trauma patients only." (PMID 39480839, 2024). "Trauma patients had significantly upregulated proteins associated with immune activation (IL-23, MIP-5), immunosuppression (IL-10) and pleiotropic cytokines (IL-29, IL-6)." (PMID 38903094, 2024). "In another study, SOD-overexpressing BM-MSCs attenuated lung epithelial cell apoptosis, inflammatory and fibrosis, and increased IL-10 levels and 30-day survival rate in radiation-induced lung injury." (PMID 37007034, 2023). "IL-17 and IL-10, which were proinflammatory and anti-inflammatory factors, respectively, played an important role in intestinal injury and brain injury." (PMID 36742316, 2023). "Administration of MSCs overexpressing IL-10 otherwise reduced structural lung injury, fibrosis, and inflammation in experimental HCl-induced lung injury." (PMID 37007034, 2023). "This cytokine has potent anti-inflammatory properties, and many studies indicated that IL-10 can modulate the inflammatory response and limit the liver damage in various animal models with liver injury." (PMID 37513833, 2023). "IL-10 when co-administered with endotoxin in animal model of brain injury counteracted the acute effects of LPS on cerebral metabolism." (PMID 34712631, 2021). "Atractylenolide I was reported to enhance IL10 expression in LPS-induced acute lung injury mouse model." (PMID 33579265, 2021). "A previous study found that peripheral blood leukocytes from trauma patients with the TLR2 rs3804099 CC genotype produce greater amounts of IL-10, IL-8, and TNF-α than those having the TT genotype, after bacterial lipoprotein stimulation." (PMID 32576967, 2020). "IL-10 is often considered as an anti-inflammatory cytokine, and a couple of works have shown that levels of inflammatory cytokine IL-10 were decreased in rats with radiation-induced lung injury." (PMID 30915142, 2019).
injury (continued). "A neuroprotective effect of IL-10 was demonstrated in rats receiving IL-10 either intracranially or peritoneally during brain injury." (PMID 29163344, 2017). "Our behavioral studies show that PD98059 prevented the upregulation of spinal protein level of IL-1beta that occurs following nerve injury and in contrast, induced the upregulation of IL-10." (PMID 26426693, 2015). "The primary effect of either endogenous or exogenous IL-10 in case of acute liver injury is the inhibition of Th1 responses." (PMID 25126542, 2014). "At these time-points IL-10 expression declined to basal or below basal levels after its maximum increase and after traumatic brain injury." (PMID 25013810, 2014). "It is thus unsurprising that administration of IL-10 reduces experimental brain injury in vivo and in vitro." (PMID 23454862, 2013). "Increases in CCL2 inhibit HIV-Tat induced apoptosis in neurons and astrocytes and increased IL-10 facilitates neuronal recovery after traumatic brain injury by reducing inflammatory cytokine production." (PMID 22901451, 2012). "Macrophages are converted into the anti‐inflammatory M2c subtype after stimulation with IL‐10 before entering apoptosis, and these macrophages limit the duration and intensity of immune and inflammatory reactions in diseases such as acute lung injury and systemic lupus." (PMID 40760821, 2025). "In addition, type-I IFN produced from liver parenchymal cells in an IRF3-dependent manner was protective in alcoholic-induced liver injury by increasing IL-10 production and decreasing TNF-α production in NPCs." (PMID 38539789, 2024). "Similarly, IL-10 is known as an anti-inflammatory cytokine upregulated after brain trauma, but can promote survival of neurons and glia in neurologic diseases including AD." (PMID 38155736, 2023). "Studies have shown that the CM of bone marrow mesenchymal stem cells (BMSCs) reduced the serum concentrations of TNF-α, IL-1β and IL-6; in contrast, the level of the anti-inflammatory cytokine IL-10 significantly increased in rats with radiation-induced liver injury." (PMID 33781342, 2021). "The study also found that protective effect of IL-37 on myocardial ischemia-reperfusion injury was significantly reduced when IL-10 signaling pathway was blocked by a specific anti-IL10R mAb, indicating that the protective function of IL- 37 at least partially depends on the involvement of IL-10." (PMID 29805973, 2018). "It is likely that the ability of IL-10 to overcome the proinflammatory milieu is temporally different between the various forms of acute brain injury, with delays resulting in prolonged inflammation that exacerbates secondary brain damage, leading to worse outcomes." (PMID 28659854, 2017). "Interestingly, Il10ra and Tnf were co‐expressed in M1 macrophages, indicating that IL‐10 could interact with M1 macrophages to trigger M1 transformation during liver injury." (PMID 39352304, 2024). "However, APAP-induced liver injury could also lead to an abnormal increase in IL-10 content because the production of IL-10 was related to the time and degree of liver injury." (PMID 35807816, 2022). "Thus, measuring VEGF, GFAP, and IL-10 soon after admission to the NICU may assist to stratify more accurately moderate–severe HI brain injury." (PMID 34795631, 2021). "In acute lung injury, Mφ-EVs in alveolar lavage fluid release various pro-inflammatory factors mainly during the early stages of damage; this activates neutrophils to produce IL-10, which might be responsible for polarizing Mφ to M2c, leading to post-acute lung injury fibrosis." (PMID 34975877, 2021). "Therefore, investigating the protective role of exosomal IL-10 in alcohol-exposed cells may provide insights in using exosomes as a therapeutic agents to reduce alcohol-induced liver injury." (PMID 30052665, 2018).
injury (continued). "Other studies have also shown that paeoniflorin could protect mice against Bacillus Calmette-Guerin or lipopolysaccharide-induced liver injury, which might be associated with the effects of inhibition of IL-1β and TNF-α release and the promotion of IL-10 production." (PMID 27525026, 2016). "The overlapping roles of cytokines, particularly IL-3, IL-6, IL-10, IL-17, TNF-α, and TGF-β, suggest significant crosstalk between pathways in radiation-induced lung injury (RILI) and immunotherapy-related lung injury (IRLI)." (PMID 40299683, 2025). "Additionally, AM is a major source of anti-inflammatory cytokines, such as IL-10 and TGF-β, which can suppress the inflammatory response to acute lung injury." (PMID 37336980, 2023). "Aerobic exercise can also modulate the inflammatory/anti-inflammatory and oxidative/antioxidative balance in the early stage of LPS-induced lung injury, which leads to a decrease in the release of inflammatory mediators such as TNF-α, IL-6, IL-10, IL-1β, IL-17, GM-CSF, and CXCL1/KC." (PMID 36456896, 2022). "However, the levels of hepatic TNF-α, IL-1β, IL-4, IL-6, and TGF-β1 were significantly lower in rats with 2-AAF/PH-induced liver injury treated with Pue and RAPA than in untreated rats with liver injury, and IL-10 expression was higher." (PMID 30405406, 2018). "Clinically, IL-10 is upregulated during the acute phase after moderate-to-severe TBI, and several pre-clinical studies report neuroprotective effects of IL-10 treatment in acute brain injury that can be attributed to its anti-inflammatory activities." (PMID 28340575, 2017). "In ConA-induced liver injury in mice, IL-10 seems to affect tolerance induction so that IL-10-knock out gene mice do not represent tolerance in ConA-induced liver injury." (PMID 26082828, 2015). "miR-30b could regulate interleukin-10 and toll-like receptor 4 expressions in T-lymphocytes, may participate in NLRP3 inflammasome expression in chronic liver injury and be involved in the inflammatory response of acute lung injury in children." (PMID 34571708, 2021). "For example, STAT3 activation by IL-6 potentiates proinflammatory responses in peritoneal macrophages, whereas STAT3 activation by IL-10 dampens lipopolysaccharide (LPS)-induced inflammatory responses in Kupffer cells, and STAT3 activation by IL-22 ameliorates ethanol-induced liver injury." (PMID 31931878, 2020). "Moreover, serum levels of IL-10 are elevated in trauma patients with and without brain injury." (PMID 28659854, 2017). "Although increases in interleukin (IL)-6, IL-8, IL-10 and glial fibrillary acidic protein (GFAP) were observed in FGR infants with brain injury, it is not clear whether similar increases would be observed in cases of more subtle brain injury in FGR infants that are not currently detectable at birth." (PMID 38966491, 2024). "Also, it has been shown that brain injury leads to increased activity of vagal nerve parasympathetic fibers, which in turn leads to downregulation of TNF-α production through the cholinergic pathway without affecting IL-10 production." (PMID 33237337, 2020).
prostate carcinoma (72 papers, 2002 to 2026). A carcinoma that arises from epithelial cells of the prostate gland. "In some cancers like cutaneous malignant melanoma and prostate cancer, the genotypes that were associated with less expression of IL-10 were a risk factor." (PMID 37501757, 2023). "Serum TRAIL and IL-10 were identified as new biomarkers for prostate cancer detection and risk stratification." (PMID 37063892, 2023). "An association between increased risk of prostate cancer or aggressive prostate cancer and IL-8 -47CT genotype as well as the IL-10 -1082GG variant was established." (PMID 34048465, 2021). "We used the following searched terms like prostate cancer, prostatic neoplasm, prostate carcinoma, prostate neoplasms, polymorphism, polymorphisms, SNP, SNPs, rs1800896, Interleukin 10, IL-10 and IL10 to identify relevant articles." (PMID 29029504, 2017). "Numerous studies have uncovered the association of Interleukin-10 (IL-10) gene rs1800896 polymorphism with the risk of prostate cancer (PCa); however, their conclusions were inconsistent." (PMID 29029504, 2017). "In the present study, we analyzed the association between 3 SNPs of the IL-10 promoter (-1082 A/G, -819 T/C, and -592 A/C) with incidence of prostate cancer in a Chinese cohort." (PMID 20735825, 2010). "We next compared the incidence of IL-10 polymorphisms in prostate cancer patients in relation to their advanced status." (PMID 20735825, 2010). "Here, we report the association of IL-10 polymorphisms with prostate cancer risk in a Chinese population." (PMID 20735825, 2010). "This study purported to investigate the impact of interleukin-10 (IL-10) gene 4 polymorphisms (−1082G>A, -819T>C, -592A>C and 210T>C) on peripheral blood IL-10 variation and prostate cancer (PCa) risk, with a special consideration given to various origins of between-study heterogeneity." (PMID 28526808, 2017). "In summary, we have discovered in our present study that while ILs-3, 6 and 11 have similar tumor promotion and stemness stimulation effects, IL-10 and IL-24 reveal opposite effects on prostate cancer cells in vitro, underlining a complex role of ILs in vivo, which merit further studies." (PMID 26528857, 2015). "Further, the decreased level of IL-10 was significant associated with prostate cancer." (PMID 16106254, 2005). "Additionally, elevated IL-10 levels have been associated with poor prognosis in high-grade prostate cancer, which may contribute to the aggressive nature of GS 10 disease." (PMID 40227503, 2025). "However, the pro-inflammatory cytokines implicated in prostate cancer pathogenesis, including IL-6, TNFa and IL-10, were readily detected in serum at concentrations reported in other mouse lines, and IL-6 was significantly increased in obese compared with lean mice." (PMID 27351281, 2016). "It is important to note that while our results align with previous research on IL-10 and its role in immune evasion, its specific impact on the progression of GS 10 prostate cancer requires further investigation." (PMID 40227503, 2025). "In models of prostate cancer, lycopene treatment induces a decrease in the concentration of inflammatory mediators such as TNF-α, IL-1β, IL-6, IL-8, IL-10, and TGF-β associated with a reduction in tumor growth and an increase in survival." (PMID 40420174, 2025). "Previous studies have explored the effects of cytokines such as IL-10 and molecules such as NE on prostate cancer." (PMID 39336493, 2024). "The CD19+PD-L1+ CD138+ IgA+ IL-10+ PC subsets in both human and murine prostate cancer models produce IL-10 and IgA and resist chemotherapy." (PMID 37033931, 2023). "As TGF-β, IL-10 and IL-6 are key factors of MDSCs and Tregs mediated immunosuppression, we next evaluated these cytokines at mRNA levels in 32 prostate cancer patients." (PMID 36138265, 2023).
prostate carcinoma (continued). "Activated eosinophils inhibited prostate cancer cell growth in vitro by secreting interleukin-10 (IL-10) and IL-12, and increasing E-cadherin expression, which putatively suppressed metastatic seeding." (PMID 36006412, 2022). "We examined the effects of exposure to human prostate cancer PC-3 spheroid-cultured media for 24 h on the expression levels of IL-10, IL-8, VEGF-A, and TGF-β1 in THP-1-derived M2 macrophages." (PMID 35955737, 2022). "Although the majority of epitopes derived from the prostate cancer antigens we identified induced IL-10 secretion, we were able to identify Th1 selective epitopes from eight of the proteins." (PMID 35948756, 2022). "In summary, CK increased cytotoxicity without hurting normal cells, sub G1 population, cleaved PARP and decreased the expression of pro-caspase-3, VEGF, TGF-β, IL-6, IL-10, Cyclin D1, c-Myc and Bcl-xL in prostate cancer cells." (PMID 34440920, 2021). "A similar scenario was also observed in prostate cancer in which IL-10 was responsible for the immune suppressive effects on T cells mediated by M-MDSCs." (PMID 32931721, 2020). "IL10 serum levels in cancer patients correlate with poor prognosis in prostate cancer patients and are positively correlated with Gleason scores." (PMID 32802517, 2020). "We found that treatment of prostate cancer cell lines in vitro with IL10 or enzalutamide induced markers of neuroendocrine differentiation and inhibited androgen receptor reporter activity." (PMID 32802517, 2020). "IL-10 is a potent immunosuppressive cytokine that has been found to play a role in a variety of human neoplasms, including gastric, colorectal, and prostate cancers." (PMID 26347589, 2015). "Nevertheless, accumulating evidence indicates that IL-10 is involved in the prostate cancer progression, as well as breast and non-small cell lung cancers." (PMID 26528857, 2015). "We have shown that IL-10 significantly inhibit the growth, migration and invasion, most probably by down regulating the cell stemness in these two prostate cancer cell lines in vitro." (PMID 26528857, 2015). "Insulin-like growth factor (IGF)-1 was previously shown to up-regulate MMP-2 production in lung cancer, whereas the interleukin (IL)-10/IL-10 receptor axis was found to down-regulate MMP-2 synthesis in prostate cancer cell line PC3 ML." (PMID 24978435, 2014). "Further it has also been observed that patients with prostate carcinoma exposed to smoking and chewing with alcohol has poor survival due to elevation in IL-10 levels which suppresses immune response mounted by increased IL-12 against cancer." (PMID 25177683, 2014). "IL-10 levels were also shown significantly increased in all combined users, (except alcohol alone) of prostate cancer group." (PMID 25177683, 2014). "Tumor infiltrating lymphocytes isolated from prostate cancers have significantly higher IL-10 expression than T lymphocytes from peripheral blood, indicating IL-10 can influence cells in the tumor microenvironment and immune response." (PMID 20946663, 2010). "IL-10 has been shown to generally suppress T cell immune responses and elevated levels of this cytokine have been detected in the serum of prostate cancer patients compared to normal healthy controls." (PMID 20946663, 2010). "A sequence variant in the promoter region of the anti-inflammatory cytokine gene IL-10 resulted in decreased levels of IL-10 in cases affected with prostate cancer." (PMID 16106254, 2005). "In contrast, other previous reports in patients with prostate cancer support the idea that circulating levels of IL-10 do not contribute to the relative risk of this type of cancer." (PMID 40722593, 2025). "In addition, the expression of IL-10 is significantly higher in PCa tumor tissues than in normal prostates and benign prostate lesions and correlates with a high grade and stage of prostate carcinoma." (PMID 39202777, 2024).